ERBB2 (erb-b2 receptor tyrosine kinase 2)
Diseases named in the same sentence as ERBB2 in open-access papers (continued):
Sharing a sentence is not in itself a finding about the gene and the disease.
breast cancer (continued). "Focusing on solid tumor markers, 2B1, a bispecific murine monoclonal antibody with bispecificity for ErbB2 and CD16 was tested in a phase I clinical trial and showed responses in breast cancer patients." (PMID 27650544, 2016). "As an example, all four genes (AKT1, BCL2, ERBB2 and VEGF) identified to change radial position after in vitro induction of early breast cancer were expressed at similar levels in the normal as compared to tumor cells." (PMID 27507988, 2016). "The best example of such targets is ERBB2, which is incidentally the only target for which an ADC (trastuzumab emtansine) is currently commercialized for the treatment of breast cancer." (PMID 26700623, 2016). "In the metastatic setting, increased MET copy numbers correlate with trastuzumab therapy failure in ERBB2-positive breast cancer and clinical trials with anti-MET therapy in advanced breast cancer are ongoing." (PMID 27576528, 2016). "Indeed, the Geldanamycin (GA) analog 17-AAG combined with TZ and TZ-TDM1 showed clinical efficacy in ERBB2+ breast cancers reporting tumor progression when treated with TZ alone, suggesting that it may represent an effective strategy to overcome, or prevent drug resistance." (PMID 27863425, 2016). "The receptor tyrosine kinase ERBB2 interacts with HSP90 and is overexpressed in aggressive breast cancers." (PMID 27863425, 2016). "Alcohol significantly increased mammosphere formation in both MCF7-ErbB2 cells and BT474 cells; BT474 cells are another breast cancer cell line with a high expression of ErbB2." (PMID 27416801, 2016). "As such, inhibition of the human epidermal growth factor receptor 2 (HER2; ERBB2 gene) represents a paradigm in breast cancer oncology." (PMID 27462779, 2016). "Soares and colleagues analyzed the status of the topoisomerase II alpha gene (TOP2A) in the FMCs referred above, as the status of these two genes, ERBB2 and TOP2A, is usually “in accordance” in some human breast cancers." (PMID 29056725, 2016). "Proliferation of MCF-7 breast cancer cells was activated by OA, most likely via transactivation of the EGFR, and OA was shown to downregulate ERBB2 in breast cancer cells." (PMID 27894086, 2016). "From a technical perspective applying RT-qPCR for resolving the status of ERBB2, ESR1, PGR, and MKI67 represents an efficient and reproducible alternative for decentralized routine assessment of breast cancer molecular subtypes." (PMID 27389414, 2016). "The oncogenetic tree model was built on CNV of ErbB2, AKT2, KRAS, PIK3CA, PTEN, and CCND1 genes in 963 cases of tumors with sequencing and CNA data of human breast cancer from TCGA." (PMID 27190992, 2016). "For example, 14-3-3ζ was found to interact with ErbB2 to regulate several important metastasis mediators including E-cadherin, fork head box protein M1 (FOXM1) and β-catenin, such as to promote breast cancer metastasis." (PMID 26730736, 2016). "In summary, our data identifies the ERBB2 co-amplified and co-expressed gene GSDMB as a critical determinant of poor prognosis and therapeutic response in HER2-positive breast cancer." (PMID 27462779, 2016). "The link between ErbB2 and the AKT pathway in breast cancers has been validated in vitro and in vivo, indicating the possible role of AKT activation in ErbB2-mediated breast cancer progression." (PMID 27190992, 2016). "This approach reconfirmed the well-established ERBB2 oncogene addiction in models of breast cancer, but also established ERBB2 addiction/KGD in models of esophageal cancer, where ERBB2 is recurrently amplified/overexpressed in 20% of tumors." (PMID 26947069, 2016). "Among various subtypes of breast cancer, overexpression and amplification of the human epidermal growth factor receptor type 2 (HER2; ErbB2/neu) accounts for about 20% of all cases and is a predictor of aggressive phenotype and poor prognosis." (PMID 26894975, 2016).
breast cancer (continued). "In breast cancer models, we found an increased requirement for ERBB3 and PIK3CA, members of the ERBB2 and PI3-kinase signaling pathways that are frequently dysregulated in this cancer histology." (PMID 26947069, 2016). "Most extensively studied however, is the role of PTP1B as tumor promoter in breast cancer, as a strong correlation is found between PTP1B and HER2 (ErBb2) overexpression." (PMID 26942883, 2016). "We first confirmed ErbB2/ErbB3 hererodimerization in ErbB2-overexpressing BT-474 and MDA-MB-453 human breast cancer cells." (PMID 27531070, 2016). "We first examined the effect of alcohol on MCF7 breast cancer cells and MCF7 cells overexpressing ErbB2 (MCF7-ErbB2)." (PMID 27416801, 2016). "Unsurprisingly, the protein products of ERBB2 and ESR1 are targets of drug and hormone therapy for breast cancer." (PMID 27112211, 2016). "Mammary tumor models can also be created using RCAS viruses expressing other oncogenes, such as a constitutively activated version of ErbB2/HER2/Neu (caErbB2)." (PMID 27376150, 2016). "To further investigate the impact of ROR1/2 overexpression in breast cancer cells, we transfected both the luminal A breast cancer cell line MCF-7 and the ERBB2/HER-2+ cell line SK-BR-3 with a ROR2 construct." (PMID 26862065, 2016). "First we characterized the WNT repertoire of the three model breast cancer cell lines MCF-7, SK-BR-3, and MDA-MB-231 representing the luminal, ERBB2/HER-2+, and basal-like molecular subtypes of breast cancer." (PMID 26862065, 2016). "Amplification of the human epidermal growth factor receptor ERBB2/HER2 gene, located in chromosomal region 17q12 occurs in around 15% of breast cancers and defines the category of clinical HER2-positive breast cancers." (PMID 27406316, 2016). "For example, trastuzumab and gefitinib respectively target ERBB2 and EGFR from the same motif, and they have been used clinically in combination to treat breast cancer." (PMID 26853265, 2016). "Human epidermal growth factor receptor 2 (HER2/ErbB2), a member of the epidermal growth factor receptor (EGFR) family, is overexpressed in several human cancers, including 20-25% of breast cancer (BC) cases and 10-30% of GC cases." (PMID 27167206, 2016). "This is supported by recent in vitro and in vivo studies that show that ERBB2 and MYC can cooperate to induce aggressiveness in breast cancer." (PMID 26018524, 2015). "For example, previous studies have shown pro-tumorigenic and pro-metastatic role of ERBB2, WNT7b, S100A7, and MMP13 in breast cancer." (PMID 26669540, 2015). "Consistent with the characteristic metabolic shift observed in cancer cells, mitochondrial localization of FGFR1 and ErbB2 contributes to reduced OXPHOS in lung and breast cancer, respectively." (PMID 26210498, 2015). "SKBR3-cells, characterized by ERBB2/RARA co-amplification, represent a subgroup of HER2+ breast-cancers sensitive to all-trans retinoic acid (ATRA) and Lapatinib." (PMID 25961594, 2015). "ErbB2/3 heterodimer is known to induce strong mitogenic response, and ErbB2 in general, plays a critical role in heregulin (HRG)-induced breast cancer cell growth and migration." (PMID 26084289, 2015). "Overexpression of ERBB2/HER-2, belonging to the ERBB family of tyrosine kinase receptors, is of great clinical importance in breast cancer, where it is tackled by the monoclonal antibody trastuzumab." (PMID 26576131, 2015). "According to the current molecular classification, breast cancers are classified into five intrinsic subtypes: normal-like, luminal A, luminal B, ERBB2/HER2 “positive” and basal-like." (PMID 26517092, 2015). "Breast cancer patients with ERBB2 amplifications are currently treated with lapatinib, a small-molecule kinase inhibitor that specifically blocks EGFR/ERBB2 signaling." (PMID 25596742, 2015).
breast cancer (continued). "Triple-negative breast cancer lacks the expression of estrogen and progesterone receptors, and human epithelial growth factor 2 receptors (HER2; also known as ErbB2), and shares characteristics with basal-like, claudin-low, and BRCA1-related breast cancer." (PMID 25514463, 2015). "As the various murine models of breast cancer display differences in latency and progression, we tested the role of Postn in MMTV-Neu (NDL2-5) mice, expressing an activated Neu/ErbB2/HER2 from the MMTV promoter." (PMID 25592291, 2015). "Breast cancer is classified into various subtypes mainly based on the immunohistochemical staining of estrogen (ER), progesterone (PR) and HER-2 (ERBB2) receptors." (PMID 26046581, 2015). "Amplification of HER-2 (human epidermal growth factor receptor 2, HER-2/ERBB2) identifies the cell as clearly a breast cancer cell and is seen progression of breast cancer." (PMID 26538094, 2015). "In breast cancer cells, ZNF217-induced overexpression of ErbB2 and ErbB3 proteins is paired with increased phospho-FAK levels." (PMID 26431164, 2015). "Five intrinsic molecular subtypes of human breast cancer include Luminal A, Luminal B, human epidermal growth factor receptor 2 (HER2/ERBB2)-positive, basal-like, and normal-like breast cancer." (PMID 25537518, 2015). "For instance, miR-206 expression was higher in ERalpha-negative MB-MDA-231 cells than in ERalpha-positive MCF-7 cells, and enforced expression of miR-125a or miR-125b led to coordinate suppression of ERBB2 and ERBB3 in the human breast cancer cell line SKBR3." (PMID 26400441, 2015). "We next determined the effect of mir-4728-3p expression on the HR for the patients in our breast cancer cohort in conjunction with all other known variables, including lymph node metastasis, TNM stage, and ER, PR, and ErbB2 positivity." (PMID 25950472, 2015). "For instance, some of the genes enriched in canine iUC samples i.e., PPARG, TBX2, ERBB2, ERBB3 are genes indicative of luminal subtypes of breast cancer in humans." (PMID 26352142, 2015). "In breast cancer, overexpression of HER2 (ERBB2) is found in approximately 10%–30% of patients and is associated with reduced survival." (PMID 26404379, 2015). "We examined molecular markers of the erbB family not just because erbB-2 is a predisposition factor of this transgenic model but also because regulation of the erbB family members plays a critical role in physiological mammary development and breast cancer pathogenesis." (PMID 25853264, 2015). "We first analyzed using qRT-PCR the expression of miR-125a-5p in a cohort of breast cancer cell lines including MDA-MB-435, MDA-MB-231, MCF-7, its HER2/ErbB2-overexpressing derivative MCF-7/Her18, R2d, and R2N1d." (PMID 25504437, 2015). "Among the genes amplified in the focal regions were a cluster of HOX genes (HOXA7, HOXA9, HOXA10, HOXA11) on 7p15, AKT1 (14q32.33), IGF1R (15q26.3), ERBB2 and NEUROD2 (17q12), all of which have been reported in primary breast cancers." (PMID 24489661, 2014). "First, treatment of SK-Br-3 breast cancer cells, which overexpress the EGFR family member ErbB2, with geldanamycin to promote receptor ubiquitination and endosomal transport, recruited FLAG-Eps15 to endosomes." (PMID 25260758, 2014). "However, the increase in expression of other miR-125b targets, such as the EGF receptor family members ERBB2/3 might be overall more relevant in breast cancer tissue, as overexpression of this gene is one of the most prominent oncogenic drivers in mammary carcinoma." (PMID 24774301, 2014). "Clinical data indicate that tamoxifen resistant breast cancers often have an increased expression of the receptor tyrosine kinase (RTK) epidermal growth factor (EGF) receptor (EGFR/ERBB1) and its family member ERBB2." (PMID 24758408, 2014). "YY1 also reportedly activates the expression of human epidermal growth factor receptor 2 (ERBB2), which is overexpressed in approximately 30% of breast cancers and correlates with poor prognosis." (PMID 24674326, 2014).
breast cancer (continued). "In the clinic, breast cancers are classified into HER2amp, hormone receptor positive (HR+), or TNBC subtypes based on the expression levels of the ErbB2 tyrosine kinase and the estrogen and progesterone nuclear hormone receptors (ER/PR)." (PMID 24655548, 2014). "The expression of ErbB2 and the stem cell marker ALDH correlate positively in human primary breast cancer." (PMID 24709902, 2014). "We find significant down-regulation of PHLDA1 in primary breast cancer and PHLDA1 is statistically significantly less expressed in ErbB2 negative compared with ErbB2 positive tumors consistent with its regulation by ErbB2." (PMID 25238247, 2014). "The majority of breast cancers are ER+, respond to estrogens, and are commonly treated with anti-hormonal and HER2 (ErbB-2) targeted therapies." (PMID 24716804, 2014). "Rare ERBB2 kinase domain mutations have recently been suggested to serve as predictive markers for ErbB2-targeted therapy in the absence of ERBB2 amplification, indicating that rare mutations may have clinical relevance in high-incidence cancers such as breast cancer." (PMID 25036186, 2014). "Overexpression and amplification of human epidermal growth factor receptor-2 (HER2, ErbB2) is present in 15 to 20% of primary human breast cancers." (PMID 24887180, 2014). "The genetic and pharmacological inhibition of ERBB3 results in anti-tumorigenic activity in cancer cells, both in vitro and as xenograft, and sensitizes lung cancer cells and breast cancer cells to lapatinib, a dual TKI of EGFR and ERBB2." (PMID 24970817, 2014). "A recent study investigated the impact of Cd151 deletion on tumor onset, growth and metastasis of another well characterized mouse mammary tumor model, the MMTV/Neu model (overexpressing multiple copies of wild-type Neu, the rat homolog of ErbB2)." (PMID 25012362, 2014). "Further in vivo analyses have shown that in the MMTV-NeuT mouse model of ErbB2 tumourigenesis, over-expression of p130Cas/BCAR1 accelerates the onset of mammary tumours, which are characterized at the molecular level by increased activation of c-Src and Akt." (PMID 25606587, 2014). "As a third application case, we selected data for a set of 26 breast cancer cell lines from the CCLE resource and studied their differential responses to lapatinib, a clinically approved dual EGFR and ERBB2 (HER2) kinase inhibitor." (PMID 24898935, 2014). "The importance of this connection is highlighted by experiments in mouse models of breast cancer, where FAK is required for ErbB2/3 mediated oncogenic transformation and lung metastases of MDA-231-M2 cell injected into the mammary fat pad." (PMID 25000176, 2014). "Seeking to demonstrate the effects of PUVA on ErbB2 signaling, we showed that steady-state protein levels of the activated, phosphorylated form of ErbB2 were reduced in PUVA-treated ErbB2+ breast cancer cell lines in a dose-dependent manner." (PMID 24551203, 2014). "For this, we analyzed four different breast cancer cell lines (MDA-MB-453, MDA-MB-361, SK-BR-3 and BT-474) each representing different copy number of the ERBB2 locus (FISH ERBB2 to CEP17 ratios equal 2.15, 3.60, 4.42, 5.79, respectively)." (PMID 24465780, 2014). "While ERBB1, ERBB2 and ERBB3 are often overexpressed or activated in breast cancer, and are oncogenic, the role of ERBB4 in breast cancer is uncertain." (PMID 25516216, 2014). "Currently, patients with trastuzumab resistant breast cancers are treated with chemotherapy and lapatinib, a dual pharmacological EGFR and ErbB2 inhibitor that targets the intrinsic kinase domains of these two receptors." (PMID 24709902, 2014). "Similar to findings in human breast cancer, we recently demonstrated that PTK6 is induced in mouse mammary gland tumors of different origins, including spontaneous tumors and ERBB2 (HER2) induced tumors." (PMID 25153721, 2014).
breast cancer (continued). "Resistance to humanized monoclonal erbB2/HER2 antibody, trastuzumab (Herceptin), has become a pivotal obstacle for targeted therapy of HER2-positive breast cancers." (PMID 24571711, 2014). "This event has also been shown in tamoxifen-treated breast cancer samples, where the PAX2-positive AIB-1-negative tumors have the best prognosis and the lowest percentage of ERBB2-positive cells." (PMID 23192763, 2013). "However, there are some reports suggesting that β-catenin activity may play a role in ErbB2+ mammary tumors, while multiple other studies suggest that the Wnt signaling-active subset of breast cells may be especially vulnerable to developing into basal tumors, which exhibit increased Wnt signaling." (PMID 24265712, 2013). "We selected two breast cancer cell lines (MDA-MB-453 and MDA-MB-157) characterized by low-intermediate levels of endogenous ERBB2, moderate-high EPOR expression and low levels of endogenous miR-125b (if compared to normal breast, data not shown)." (PMID 24165569, 2013). "Breast cancer therapies that target cell surface proteins, such as EGFR and ERBB2 are rare examples of successful biologically informed cancer treatments." (PMID 23840623, 2013). "As assessed by ddPCR, four out of twenty tumors carried a HER2/ERBB2 amplification, which is consistent with data for human breast cancer, where the amplification has an incidence of 15–25%." (PMID 24098698, 2013). "In human breast cancer (HBC), erbB-2 protein overexpression has been repeatedly correlated with poor prognosis." (PMID 24386251, 2013). "In our panel of cancer cell lines, there were four breast cancer cell lines (ZR-75-1, SKBR3, MDA-MB-231, and MCF7) among which only two cell lines were considered to overexpress ErbB2, SKBR3, which is scored at 3+, and ZR-75-1, which is scored at 2+." (PMID 23519149, 2013). "In breast cancer, EGFR and ErbB2 expression was found to be under control of the Y-box transcription/translation factor YB1 which is phosphorylated by Akt." (PMID 24304721, 2013). "Since EPOR and ERBB2 are both target of the tumor suppressor miR-125b, we searched for a correlation between EPOR and ERBB2 expression in an independent cohort of breast cancers." (PMID 24165569, 2013). "Furthermore, we reveal sets of miRNAs associated with genes frequently amplified (ERBB2) or mutated (p16INK4a, PIK3CA and/or PTEN, E-cadherin, BRCA1) in breast cancer cell lines and thus these miRNAs may contribute to the function of these oncogenes/tumor suppressors." (PMID 23601657, 2013). "Experimentally, miR-125-induced down-regulation of ERBB2 and ERBB3 has been uncovered to reduce cell motility and invasiveness of numerous cancers, including breast cancer and endometrial cancer." (PMID 23321005, 2013). "Our recent studies indicate that erbB3 interacts with both erbB2 and IGF-1 receptor to form a heterotrimeric complex in trastuzumab-resistant breast cancer cells." (PMID 24215614, 2013). "It has been reported that fulvestrant-resistant breast cancer cells were able to utilize Wnt/β-catenin and EGFR/ErbB2 signaling pathways to establish estrogen-independence and autocrine-regulated proliferation." (PMID 24137320, 2013). "In leiomyoma, IPA shows a network connection between ERBB2 and DPT, a relationship previously undisclosed in studies of uterine leiomyoma or, to our knowledge, in studies of breast cancer." (PMID 23785396, 2013).